RNU6-1309P (RNA, U6 small nuclear 1309, pseudogene)
Gene: Small nuclear RNA gene on chromosome 1 (150,812,591 to 150,812,698, reverse strand). Ensembl gene ENSG00000200175.
Homologues: Orthologues: chimpanzee U6 (100% identical), macaque U6 (94% identical), rabbit U6 (88% identical), guinea pig U6 (77% identical), pig U6 (77% identical), guinea pig U6 (75% identical), mouse Gm55761 (72% identical). Paralogues in human: RNU6-774P (91% identical), RNU6-727P (90% identical), RNU6-11P (89% identical), RNU6-24P (89% identical), RNU6-37P (89% identical), RNU6-43P (89% identical), RNU6-560P (89% identical), RNU6-742P (89% identical), RNU6-1209P (88% identical), RNU6-33P (88% identical), RNU6-34P (88% identical), RNU6-767P (88% identical), and 1289 more.